PRAMEF18 (PRAME family member 18)
Tractability: No criterion of Open Targets' tractability assessment is met for any kind of drug.
Gene: Protein-coding gene on chromosome 1 (13,222,695 to 13,226,154, reverse strand). Ensembl gene ENSG00000279804.
Gene Ontology:
Molecular function: ubiquitin-like ligase-substrate adaptor activity
Biological process: proteasome-mediated ubiquitin-dependent protein catabolic process; negative regulation of apoptotic process; negative regulation of cell differentiation; negative regulation of DNA-templated transcription; positive regulation of cell population proliferation
Cellular component: Cul2-RING ubiquitin ligase complex; cytoplasm
Genetic constraint (gnomAD): Loss-of-function variants: 15 observed, 16.77 expected, observed/expected ratio (o/e) 0.89, 90% interval 0.6 to 1.38. The upper end of that interval is the gene's LOEUF score, 1.38, which puts it in group 5 of 6, group 1 being the genes least tolerant of losing a copy. Missense variants: 216 observed, 245.04 expected, observed/expected ratio (o/e) 0.88, 90% interval 0.79 to 0.99. Synonymous variants: 71 observed, 82 expected, observed/expected ratio (o/e) 0.87, 90% interval 0.71 to 1.05.
Homologues: Orthologues: mouse Pramel12 (44% identical), rat Pramef8 (44% identical), rat LOC120103107 (41% identical), mouse Pramel13 (41% identical), mouse Pramel36 (41% identical), mouse Pramel46 (41% identical), mouse Pramel49 (41% identical), mouse Pramel43 (40% identical), mouse Pramel21 (40% identical), mouse Pramel11 (40% identical), mouse Pramel24 (40% identical), mouse Pramel32 (40% identical), and 78 more. Paralogues in human: PRAMEF19 (92% identical), PRAMEF10 (62% identical), PRAMEF1 (62% identical), PRAMEF33 (62% identical), PRAMEF17 (61% identical), PRAMEF14 (61% identical), PRAMEF2 (60% identical), PRAMEF13 (60% identical), PRAMEF12 (54% identical), PRAMEF20 (52% identical), PRAMEF8 (51% identical), PRAMEF7 (51% identical), and 12 more.